GREM1 (gremlin 1, DAN family BMP antagonist)
Diseases named in the same sentence as GREM1 in open-access papers (continued):
Sharing a sentence is not in itself a finding about the gene and the disease.
lung carcinoma (17 papers, 2006 to 2025). "Consistent with our analytic data, elevations of GREM1 expression were visible in numerous solid tumors, such as lung cancer, kidney cancer, and gastric cancer." (PMID 36091126, 2022). "In REMI-LUAD, known lung cancer–specific LR pairs were identified, including GREM1:KDR, which was experimentally validated between fibroblast and malignant cells." (PMID 35302849, 2022). "Some lung cancer cell lines express high levels of GREM1, suggesting a potential tumor-promoting autocrine role in a subset of lung cancers." (PMID 32381040, 2020). "Based on the results from the LTMI, we sought to functionally test if GREM1 can alter behavior of lung cancer cells." (PMID 32381040, 2020). "Lung cancer cell lines express GREM1 at varying levels, with ~ 5500-fold range across SCC lines and nearly 13,000-fold across adenocarcinomas as measured in the Cancer Cell Line Encyclopedia." (PMID 32381040, 2020). "The four genes, GREM1, LOXL2, ADAMTS12 and ITGA11, provide a candidate stromal signature that may be functionally implicated in lung cancer dissemination." (PMID 29503225, 2018). "Thus, exogenous GREM1 increases aggressiveness of lung cancer cells in vitro." (PMID 32381040, 2020). "Altogether our data suggest that expression of GREM1, LOXL2, ITGA11 and ADAMTS12 by MSCs enhances primary lung cancer metastasis." (PMID 29503225, 2018). "For instance, MSCs derived from normal lung tissue stimulated by TME are transformed into TA-MSCs expressing high levels of gremlin 1 (GREM1), lysyl oxidase-like 2 (LOXL2), integrin α 11 (ITGA11), which promote invasion and metastasis of lung cancer cells via stromal pro-metastatic signaling." (PMID 35842634, 2022). "For other IRGs, such as LGR4, GDF10, GREM1, IL20RB, INHA, VIPR1, and ADM2, they had been verified to participate in carcinogenesis and affect patients’ prognoses in other cancers, although the relevant studies were rare in lung cancer." (PMID 33386920, 2021). "Hypermethylation of GREM1 is identified for prognostic significance in renal cell carcinoma, so far not in lung cancer." (PMID 24369052, 2013). "We obtained five key genes such as GREM1, MMP11, SPP1, FOSB, and IL33 which were strongly associated with lung cancer in nonsmoking women, which improved understanding and could serve as new therapeutic targets, but their functionality needs further experimental verification." (PMID 34671675, 2021).
colon cancer (16 papers, 2013 to 2025). "These HMPS patients develop intestinal polyps and a colon cancer phenotype due to a tissue compartment switch in expression of GREM1 from intestinal stromal to epithelial cells." (PMID 37615860, 2023). "Consistently, siRNA-mediated targeting of GREM1 in mesenchymal-like colon cancer cells (e.g. SW620) led to the suppression of cell growth and angiogenesis." (PMID 37615860, 2023). "It is worth mentioning that EMT in colon cancer cells can be suppressed by silencing of GREM1 with shRNA, and EMT is considered a critical event inducing morphogenetic changes during the process of embryonic development." (PMID 33962391, 2021). "GREM1 tissue expression is associated with EMT and coordinates migration at the cancer invasion front in colon cancer." (PMID 29404274, 2017). "Higher GREM1 mRNA expression was observed in colon tumor tissues compared with adjacent normal tissues." (PMID 28977865, 2017). "Interestingly, expression of GREM1 protein was also detected in AKP colonic tumors, with strong staining at the basolateral surface of colonic epithelial cells." (PMID 41033552, 2025). "Besides, in our study, we did not observe the formation of intestinal polyps or the induction of colon cancer because of targeted delivery of Grem1." (PMID 39990215, 2025). "GREM1 as enCAF maker gene was highly expressed in colon cancer tissues." (PMID 35910200, 2022). "GREM1 in Caco2 colon cancer cells inhibits differentiation by suppressing p21/CKDN1A expression." (PMID 35883579, 2022). "Furthermore, analysis of expression microarray data from 556 patients with primary colon cancer confirmed that the GREM1-high and ISLR-low groups each independently exhibited poor overall survival." (PMID 33197448, 2021). "It is worth mentioning that the epithelial-mesenchymal transition (EMT) in colon cancer cells can be suppressed by silencing of GREM1 via short hairpin RNA (shRNA), and this process is considered an essential event inducing morphogenetic changes during the development of embryos." (PMID 33962391, 2021). "Moreover, higher expression level of GREM1 was investigated in colon tumor tissues compared with adjacent normal tissues using TCGA data." (PMID 28977865, 2017). "Moreover, increased expression of GREM1 has also been recently found in colorectal polyps, as well as in the dysplasia to carcinoma transition in colon tumors." (PMID 25253512, 2014). "GREM1-mediated angiogenesis (potentially via VEGFR2 singalling) has been identified in pancreateic neuroendocrine tumors, colon cancer and diffuse intrinsic pontine glioma." (PMID 37615860, 2023). "Of special note, two key marker genes, GREM1, and IGF1, were significantly differently expressed in 20 pairs of colon cancer and paracancerous tissues." (PMID 35910200, 2022). "As expected, the treatment of microRNA hsa-miR-185-3p on colon cancer cells reduced the expression of GREM1 when compared with the treatment of negative control (P=0.019)." (PMID 28977865, 2017). "Interestingly, lower expression of a number of genes (GREM1, LOX, TNFAIP6, CD36, and EDNRA) predicted better prognosis in both ovarian and colon cancers." (PMID 23536776, 2013).
pulmonary fibrosis (16 papers, 2013 to 2026). Chronic progressive interstitial lung disorder characterized by the replacement of the lung tissue by connective tissue, leading to progressive dyspnea, respiratory failure, or right heart failure. "DMB treatment of a mouse model of pulmonary fibrosis led to disruption of GREM1 deubiquitination and GREM1 protein degradation." (PMID 40277903, 2025). "In conclusion, we reported that DMB alleviated pulmonary fibrosis by promoting GREM1 degradation through Ub/proteasome pathway." (PMID 38543064, 2024). "GREM1 is one of the major BMP antagonists and aberrant expression of GREM1 contributed to pulmonary fibrosis." (PMID 38543064, 2024). "An increasing number of studies have demonstrated that GREM1 has a profibrotic effect and contributes to pulmonary fibrosis, renal fibrosis and colonic fibrosis." (PMID 38543064, 2024). "In mouse models of lung fibrosis, inflammatory fibroblasts expressing Grem1 play a key role at inducing the early pathological steps changes associated with the onset of fibrosis." (PMID 37615860, 2023). "The mRNA level of GREM1 is highly up-regulated in lung biopsies of patients with idiopathic pulmonary fibrosis." (PMID 32141512, 2020). "Therapeutic strategies targeting GREM1 have shown potential in the treatment of pulmonary fibrosis." (PMID 41007698, 2025). "Treatment with DMB compound was shown to alleviate pulmonary fibrosis in vivo, demonstrating that specific targeting of GREM1 in the lung may provide therapeutic benefit." (PMID 40277903, 2025). "GREM1, part of the TGF-β superfamily, contributes to pulmonary fibrosis during the early stages of disease." (PMID 41489684, 2026). "Gremlin-1 (GREM1) belongs to the family of BMP antagonists and is upregulated in mice and clinical patients with pulmonary fibrosis." (PMID 38543064, 2024). "Our results indicated that GREM1 was significantly upregulated in IPF patients and mice with pulmonary fibrosis and downregulated after DMB treatment." (PMID 38543064, 2024). "High throughput sequencing analysis indicated that GREM1, a highly upregulated profibrotic mediator in IPF and BLM-induced pulmonary fibrosis, was significantly downregulated by DMB." (PMID 38543064, 2024).
osteoarthritis (15 papers, 2013 to 2025). A noninflammatory degenerative joint disease occurring chiefly in older persons, characterized by degeneration of the articular cartilage, hypertrophy of bone at the margins and changes in the synovial membrane. "Loss of these GREM1-lineage chondrogenic progenitor cells has been linked to osteoarthritis in mice, involving perturbations in FGF18 → FGFR3 signaling." (PMID 40277903, 2025). "In this study, we investigated whether factors implicated in osteoarthritis or regulation of chondrocyte hypertrophy influence GREM1, FRZB and DKK1 expression levels." (PMID 24286177, 2013). "Since osteoarthritis is associated with deregulated hypertrophic differentiation in at least a subset of patients, we hypothesized that GREM1, FRZB and DKK1 mRNA expression levels are downregulated in osteoarthritis." (PMID 24286177, 2013). "Regeneron have also developed a GREM1 neutralizing antibody aimed at treating both fibrosis and cancer, and has been shown to attenuate osteoarthritis in a mouse model." (PMID 40277903, 2025). "Inflammatory conditions such as osteoarthritis and renal inflammation and damage are promoted by GREM1 overexpression, potentially via VEGFR2 signaling." (PMID 37615860, 2023). "Studies have shown that Grem1 is significantly upregulated in human osteoarthritis and animal models of osteoarthritis." (PMID 35440754, 2022). "GREM1 can also activate nuclear factor-κB signaling, leading to subsequent induction of catabolic enzymes and osteoarthritis." (PMID 33287358, 2020). "Together, the current study demonstrates an inverse correlation between osteoarthritis and GREM1, FRZB and DKK1 gene expression in cartilage and provides insight into the underlying transcriptional regulation." (PMID 24286177, 2013). "Thus, they targeted these factors by inhibiting the miR-23a/b-3p or overexpressing the Grem1 which resulted in attenuating the progression of the degenerative joint diseases." (PMID 33383629, 2020). "Moreover, we demonstrated an association between a genetic variation (SNP rs12593365) in a genomic control region of GREM1 and radiographic osteoarthritis of the hip." (PMID 24286177, 2013). "Higher levels of GREM1 and S100A6, however, correlate with osteoarthritis, opposing the expression of NID2 and EDIL3." (PMID 40224957, 2025). "The current study demonstrates that the mRNA expression of GREM1, FRZB and DKK1 is inversely correlated with the level of cartilage degeneration in osteoarthritis." (PMID 24286177, 2013). "GREM1, FRZB and DKK1 mRNA expression were strongly decreased in osteoarthritis." (PMID 24286177, 2013). "Based on these observations, we hypothesized that the expression of GREM1, FRZB and DKK1 is inversely correlated with osteoarthritis and their expression is influenced by established regulators of chondrocyte hypertrophy." (PMID 24286177, 2013).
cervical cancer (14 papers, 2006 to 2025). A primary or metastatic malignant neoplasm involving the cervix. "Some studies have linked high GREM1 expression to poor prognosis in several malignancies, including ER-negative breast cancer, cervical cancer, ex-trahepatic cholangiocarcinoma, basal cell carcinoma and renal cell carcinoma." (PMID 35883579, 2022). "On another note, high GREM-1 expression in cervical cancer tissues was reported to be a prognostic factor of overall survival and correlated with bulky tumor size." (PMID 35203511, 2022). "The Wnt-driven GREM1 as a carcinogenic gene promoting proliferation in cervical cancer and the Wnt target gene AXIN2 were upregulated in xenograft tumors from LGR6high HeLa, SiHa, and CaSki cells." (PMID 34489551, 2021). "Treatment of cervical cancer cells with GREM1 can significantly increase expression levels of cancer stem cell markers and the ability of cancer cells to form spheroids." (PMID 33287358, 2020). "Additionally, LYPLA1 was found to be highly expressed in malignant cervical cancer tissues, where it was associated with the upregulation of EMT-inducing TIAM1 and GREM1 and a decrease in mesenchymal markers." (PMID 37644433, 2023). "In summary, these results clarify that circ_0007534, as a sponge of miR-206, upregulates GREM1 expression, promotes cervical cancer progression in vitro and cervical cancer tumorigenesis in vivo, and is expected to be a novel tumor marker for cervical cancer diagnosis and prognosis." (PMID 36505874, 2022).
diabetic nephropathy (13 papers, 2013 to 2023). "Gene Grem1 and Slc7a9 are associated with diabetic nephropathy." (PMID 32523943, 2020). "Other studies propose GREM1 as an important mediator for diabetic kidney disease, and due to its interaction with TCF7L2, which facilitates its DNA binding, it can be considered one of the common genetic factors for T2DM and CRC." (PMID 35893034, 2022). "Grem1 levels are increased in renal fibrotic conditions, including acute kidney injury, diabetic nephropathy, chronic allograft nephropathy, and immune glomerulonephritis." (PMID 28100499, 2017). "Grem1 levels are increased in diabetic nephropathy (DN), chronic allograft nephropathy, immune glomerulonephritis, and acute kidney injury (AKI)." (PMID 28100499, 2017). "In biopsies from patients with diabetic nephropathy, we have demonstrated that GREM1 is expressed in areas of tubular-interstitial fibrosis and that it colocalizes with profibrotic markers, including TGF-β, αSMA and vimentin." (PMID 25036148, 2014). "In a streptozotocin-induced model of type 1 diabetes, knockout mice heterozygous for Grem1 gene deletion (Grem1+/-) exhibit protection from the progression of diabetic kidney disease." (PMID 23394397, 2013).
pancreatic cancer (13 papers, 2018 to 2025). "The analysis lead to the identification of TIMP-1, FN-1, SPARC, IGFBP-3, LGALS3BP, and GREM1 as the most upregulated glycoproteins in early-stage pancreatic tumor tissues as compared to controls." (PMID 40345589, 2025). "High levels of GREM1 were also detected in pancreatic stellate cells in the stroma of pancreatic tumors." (PMID 40277903, 2025). "GREM1 expression in these cells was increased by Shh signaling, contributing to a fibrogenic stromal microenvironment and pancreatic cancer cell progression." (PMID 40277903, 2025). "In human cancer, GREM1 expression has been demonstrated in pancreatic stellate cells (PSCs), and is driven by Shh → Gli1 signaling, enabling pancreatic cancer progression." (PMID 40277903, 2025). "Elevated GREM1 mRNA has been identified in a wide range of human cancers including colorectal, breast, glioma, gastric and pancreatic cancer." (PMID 37615860, 2023). "In contrast, a report recently emerged that GREM1 signaling contributes to inhibition of pancreatic tumor growth and cancer progression." (PMID 37615860, 2023). "In contrast, a 2022 report revealed that GREM1 can promote an epithelial state in pancreatic cancers, thereby inhibiting pancreatic tumor growth and metastasis." (PMID 37615860, 2023). "Delivery of Grem1 neutralising antibodies that inhibit Grem1 binding to target Bmps to in vivo mouse models of pancreatic cancer would allow investigators to assess whether this leads to improved or worsened tumor volume and outcomes." (PMID 37615860, 2023). "Interestingly, CC-3 subcluster highly expressed Grem1, which has been shown to regulate pancreatic cancer cell heterogeneity by recent studies." (PMID 37190324, 2023). "Concerning the bioinformatics analysis results, serum GREM1 level significantly increased in the PDAC group compared to the HC group, as well as different elevations in assorted pancreatic neoplasms, especially IPMN." (PMID 36091126, 2022). "Serum GREM1 levels in PDAC and other pancreatic neoplasms were obtained at varying degrees of elevation, compared to the HC group (p < 0.05)." (PMID 36091126, 2022). "Furthermore, silencing of GREM-1 negatively regulated the proliferation and migration of pancreatic stellate cells as well as the proliferation, invasion, and EMT of AsPC-1 and BxPC-3 pancreatic cancer cell lines." (PMID 35203511, 2022).
pulmonary hypertension (12 papers, 2014 to 2025). Increased pressure within the pulmonary circulation due to lung or heart disorder. "The first report detailing an anti-GREM1 neutralizing antibody was from Novartis, who showed that targeting GREM1 could reduce pulmonary artery hypertension in mice." (PMID 40277903, 2025).
basal cell carcinoma (11 papers, 2012 to 2022). A carcinoma involving the basal cells. "Interestingly, cancer‐associated fibroblasts (CAFs) of human basal cell carcinomas have high levels of GREM1 expression, which promote the proliferation of cultured BCC cells." (PMID 33107676, 2020). "Associations between GREM1 and immunohistochemical markers in basal cell carcinomas." (PMID 28346486, 2017). "Interestingly, Grem1 has been shown to be widely upregulated in the underlying stroma of cutaneous basal cell carcinomas when compared to normal stroma in skin." (PMID 23840733, 2013). "Overexpression of GREM1 in the tumor-supportive tissue of basal cell carcinoma, as well as carcinomas of the bladder, breast, lung, colon, and pancreas has been shown to promote tumor cell proliferation in vitro and disease progression in vivo." (PMID 32756430, 2020). "In conclusion, GREM1 is frequently expressed by myofibroblasts in scars or in the stroma of basal cell carcinomas, suggesting that GREM1 expression can be a marker for activated myofibroblasts in the cancer stroma or in scar tissue." (PMID 28346486, 2017). "Other reports have identified GREM1 expression in basal cell cancer CAFs." (PMID 31384391, 2019). "Although GREM1 has not been associated with hernia formation or wound healing, it has been found in the stromal cells of basal cell carcinomas." (PMID 22648066, 2013).
fibrosis (10 papers, 2013 to 2025). the formation of excess fibrous connective tissue in an organ or tissue in a reparative or reactive process. "A study examining GREM1 variations among sarcoidosis patients with and without fibrosis on chest radiography revealed that carriers of the GREM1 CC genotype exhibited elevated gremlin levels and were at a 6.4-fold higher risk of developing fibrosis." (PMID 38202248, 2023). "When RNA from kidney poles was analyzed, Grem1 levels were significantly increased in wild-type mice, consistent with previous data showing that Grem1 is a fibrosis-associated gene." (PMID 28100499, 2017). "The expression of GREM1 in several murine fibrosis models is greatly increased, while BMP signaling is decreased." (PMID 37235555, 2023). "The findings in the literature support a role for GREM1 in fibrosis of the skin and kidney and are suggestive of a role in hernia formation." (PMID 22648066, 2013). "Furthermore, we detected GREM1 mRNA expression in intestinal fibrosis tissue and found that GREM1 mRNA expression was also upregulated in fibrosed colon." (PMID 33967807, 2021). "However, the role of GREM1 in intestinal fibrosis remains unknown." (PMID 33967807, 2021).